IL27 (interleukin 27)
Diseases named in the same sentence as IL27 in open-access papers (continued):
Sharing a sentence is not in itself a finding about the gene and the disease.
tumor (continued). "Prior to conducting the assay, we identified a subset panel of factors known to mediate the induction of apoptosis in tumor cells: IL-27, IL-1b, IL-2, CXCL10, IL-12p70, G-CSF, IFN-g, TNF-a, IFN-a, CCL2, IL-9, TNF-b, TRAIL, IL-18, IL-21, TSLP." (PMID 37468934, 2023). "Overall, the combination of IL-27 and cabo can immunomodulate the tumor microenvironment in the bone by activating anti-tumor immune cells and suppressing anti-inflammatory responses." (PMID 37842640, 2023). "Bone metastasis is the leading contributor to PCa related morbidity and IL-27 is a promising therapeutic due to a combination of its anti-tumor and its pro-osteogenic effects." (PMID 37842640, 2023). "The therapeutic effects of IL-27 and cabo extend beyond tumor reduction, with significant improvements in bone quality." (PMID 37842640, 2023). "This work demonstrates the synergistic effects of IL-27 and cabo in reducing the tumor burden, immuno-modulating the tumor microenvironment, and improving bone health." (PMID 37842640, 2023). "IL-27 plays a role in regulating inflammation within the tumor microenvironment and influences the proliferation, survival, and invasiveness of tumor cells." (PMID 37762066, 2023). "Tumor-derived cytokines such as IL-6 and IL-27 have promoted PD-L1+CD8+ T cells development through STAT1/STAT3 signaling." (PMID 37077914, 2023). "Volcano plots showed that the gene expression in IL-27 treated tumors changed the least among all groups, potentially due to sustained IL-27 expression leading to consistent modulation of genes in the tumor microenvironment." (PMID 37842640, 2023). "The anti-tumor effects of IL-27 and cabo, along with their pro-osteogenic properties, make them promising candidates for PCa therapy." (PMID 37842640, 2023). "The combination of IL-27 and cabo demonstrates enhanced anti-tumor effects, modulates the tumor microenvironment, and improves bone quality." (PMID 37842640, 2023). "In vivo experiments investigating the combination of IL-27 gene therapy combined with cabo demonstrated the potent inhibition of tumor growth by the combination compared to the monotherapy groups and the control group." (PMID 37842640, 2023). "Such pre-clinical studies paved the way for using exogenous IL-27 as an anti-tumor immunotherapeutic." (PMID 37842640, 2023). "A total of 1620 differentially expressed genes (DEGs) were upregulated and 3724 DEGs were downregulated in the IL-27 treated tumor compared to the control vector-treated tumor." (PMID 37842640, 2023). "Our experiments reveal that IL-27 and cabo therapy enhance the immunogenicity of the tumor microenvironment, promoting an anti-tumor immune response." (PMID 37842640, 2023). "The overall impact of IL-27 gene therapy on the tumor microenvironment was assessed by initially implanting subcutaneous TC2Ras tumors in mice followed by the intramuscular delivery of plasmid expressing IL-27pepL or a control plasmid, aided by sonoporation." (PMID 37842640, 2023). "Interleukin-27 (IL-27) is a versatile heterodimeric cytokine that has anti-tumor potential and has demonstrated limited toxicity in pre-clinical studies." (PMID 37842640, 2023). "In vitro differentiation assays were performed to elucidate the tumor-independent effects of IL-27 and cabo on bone cells including osteoblasts (OB) and osteoclasts (OC)." (PMID 37842640, 2023). "IL-27 and cabo can improve bone quality in tumor-bearing mice by directly reducing tumor burden; additionally, it was found that IL-27 and cabo have direct activity on bone cells." (PMID 37842640, 2023). "We recently revealed that the cytokine IL-27 exerts a strong anti-tumor role in CLL through a T-cell-mediated mechanism." (PMID 37937211, 2023). "As such, intratumor delivery of CCL5 mRNA with LNPs was shown to significantly reduce tumor growth, and IL-27 was found to induce robust CCL5 production by T cells resulting in antitumor activity." (PMID 37805495, 2023).
tumor (continued). "While previous investigations have reported a direct cytotoxic effect of IL-27 in several malignancies, our data strongly suggests that T cells are the main mediators in the observed IL-27-driven anti-tumor immunity in CLL." (PMID 37937211, 2023). "First, the impact of IL-27 gene therapy, delivered to tumor bearing mice, was determined by sequencing the total RNA isolated from the tumors." (PMID 37842640, 2023). "On the contrary there was an increase in the Th2 mediators IL-4, IL-6, IL-27, soluble chemokine ligands and pro-inflammatory mediators responsible for promoting pro-tumor immune cells; MCP-1, and IL-16." (PMID 35154142, 2022). "In the present study, we examined how different protocols were used to generate a DTCV in combination with recombinant mouse (rm)IL-27 as an adjuvant, impact tumor growth focusing on the potential MHC-I/CD8+ T cell interactions." (PMID 35529885, 2022). "The serum levels of both IL-9 and IL-27 were significantly higher in the probiotic group compared with the model group, which potentially played a role in inhibiting tumor growth." (PMID 36615662, 2022). "This Gen 2 targeted IL-27 cytokine deploys a bispecific-anchored design to effectively target PCa tumor cells with the pepL module while inducing simultaneous anti-tumorigenic and pro-osteogenic responses through the pepL and IL-27p28 modules, respectively." (PMID 35200430, 2022). "Due to the inhibiting effect of IL-2, IL-24 and IL-27 on EC cells, there are bright prospects for them to be used as anti-tumor drugs." (PMID 36531027, 2022). "Our targeted IL-27 cytokine deploys a bispecific-anchored design to effectively target PCa tumor cells with the pepL module while inducing simultaneous anti-tumorigenic and pro-osteogenic responses through the pepL and IL-27p28 modules, respectively." (PMID 35200430, 2022). "In tumor-bearing animals, IL-27 downregulated the expression of FoxP3 in CD4+ and CD8+ T cells and prevented generation and expansion of Tregs, immunosuppressive T cells which inhibited antitumor immunity in IL-10- and TGF-β-dependent manner." (PMID 35757015, 2022). "Such dual roles make investigation of effects of the IL27 in the tumor immune environment a challenge." (PMID 36713514, 2022). "IL-27 potentiates anti-tumor immunity by both central immnunomodulatory effect of stimulating the development of NK cells and cell toxic lymphocytes (CTLs) and local antitumor effect of exerting potent anti-angiogenic and anti-metastatic activities." (PMID 36531027, 2022). "Histochemical detection in the tumor tissues revealed differences in the abundance and expression of IL-9, IL-27, and IL-5RA positive cells between probiotic and model groups, and such differences were consistent with changes in the serum cytokine profile." (PMID 36615662, 2022). "By day 21, the 27→18 combination reduced tumor volume by ~21–52% relative to IL-27, IL-18, or vector control." (PMID 34209203, 2021). "In cytokine and chemokine array analyses the overexpression of Lrp5 reduced the levels of several tumor-promoting factors in CM, including CXCL2, GM-CSF, IL6, LIF, DLK1 and MRP with an increase in IL27, a tumor-suppressing cytokine." (PMID 33859739, 2021). "Other studies have demonstrated the ability of IL-27 to modulate the NK cells’ anti-tumor cytotoxicity responses." (PMID 34440725, 2021). "IL-27 can provide anti-tumor effects but also can down-regulate T cells and up-regulate immune checkpoint proteins PD-1 and PD-L1." (PMID 34855926, 2021). "IL-27 can also potentiate anti-tumor immunity by supporting the differentiation and expansion of myeloid progenitor cells into anti-tumorigenic M1 macrophages." (PMID 33418929, 2021). "Consistently, a tumor-suppressive cytokine, IL27, was elevated in BM CM, while its level was reduced in Hsp90ab1 siRNA-treated osteoclast-derived CM." (PMID 34830748, 2021).
tumor (continued). "Considering that CD8+ T cells can directly eliminate tumor cells, we decided to further investigate the relationship between IL27 and CD8+ T cells." (PMID 34733272, 2021). "IL-27 also downregulates multiple stemness-related genes in lung adenocarcinoma and squamous cell carcinoma cell lines and inhibits tumor cell growth in xenograft models." (PMID 34045653, 2021). "Further studies are needed to examine the role of IL-27 in remodeled tumor microenvironment induced by cellular interactions involving cancer cell and immune cells such as mast cells and macrophages." (PMID 34234781, 2021). "IL27 is an immunomodulatory cytokine that plays pleiotropic roles in the context of tumor immune environment (TME)." (PMID 34733272, 2021). "Because IL-27 functions in many different cell types, not only immune cells, but also hepatocytes and tumor cells, it is considered to be an immunotherapeutic agent." (PMID 33525571, 2021). "These overall pro-inflammatory effects of IL-27 can stimulate anti-tumor immunity and contribute to tumor cell clearance." (PMID 33418929, 2021). "Study shows that IL27 exerts anti-tumor effects in PC cells by inducing cell cycle arrest and apoptosis." (PMID 33754011, 2021). "If the patients were grouped by tumor size (± 7 cm) and studied by Kaplan–Meier analyses, both IL-6 (p = 0.014) and IL-27 (p = 0.001) predicted recurrence among patients with large tumors (diameter > 7.0 cm)." (PMID 32621022, 2021). "With regards to tackling the potential pro-tumor activity of IL-27, several studies have shown that IL-27 can regulate the immunosuppression and exhaustion of T cells." (PMID 33418929, 2021). "Limited in vitro data showed enhanced immune effector activity when NK cells were ‘primed’ with IL-27, and had enhanced cytotoxic effect against tumor cells in culture, but the potential for in vivo tumor reduction remained untested." (PMID 34209203, 2021). "Utilizing single-chain IL-27-secreting colon carcinoma and murine neuroblastoma models, it was shown that these tumor cells induce robust antitumor immune responses." (PMID 34045653, 2021). "Since IL-27 can induce PD-L1 expression in different tumor cell types, we assessed IL-27’s capability of upregulating PD-L1 expression in human MM cell lines as compared to the sIL-6R/IL-6 chimera." (PMID 34439164, 2021). "IL-27 directly inhibits cancer growth or invasiveness, showing immune-enhancing activity in different in vivo tumor models." (PMID 34830209, 2021). "IL-27 also enhanced the expression of inducible nitric oxide synthase, which sustained the anti-tumor activity of macrophages within the TME." (PMID 33418929, 2021). "Altogether, these combined analyses suggest that IL27 acts as a driver gene and has an anti-tumor effect." (PMID 34733272, 2021). "Another protein with double function pro-and anti-tumour functionality is IL-27, which belongs to the IL-12 family and is known for its ability to inhibit angiogenesis and activate NK cells." (PMID 34283046, 2021). "IL-27 also has direct transcriptional effects on several cell types, including tumor cells, and is able to induce natural killer (NK) and cytotoxic T lymphocyte responses, while reducing angiogenesis through CXCL9-10 upregulation." (PMID 34209203, 2021). "IL-23 and IL-27 play dual roles in tumor immunity, as they can both activate effector immune responses and promote tumor growth by favoring immune suppression." (PMID 33418929, 2021). "When testing IL-27 vectors and IL-18 together for potential synergy, we observed a significant reduction in tumor growth rate by day 15 relative to the control vector alone." (PMID 34209203, 2021). "In a mouse model of PC treated by IL-27, it has been revealed that this cytokine therapy can inhibit tumor cell growth and proliferation, reducing tumor size." (PMID 34868907, 2021).
tumor (continued). "The potent anti‐tumour activity of the IL‐12 family cytokines has been put under investigation, and while the anti‐tumour activity of IL‐12 and IL‐27 has been clearly established, the role of IL‐23 appears to be controversial." (PMID 34235838, 2021). "Using NRAS/AKT-derived spontaneous HCC mouse models, we reveal an IL-27–independent tumor-suppressive effect of WSX1 that largely relies on CD8+ T-cell immune surveillance via reducing neoplastic PD-L1 expression and the associated CD8+ T-cell exhaustion." (PMID 34108491, 2021). "IL27 is an immunomodulatory cytokine that can induce anti-tumour CD8 T cell responses in the tumour microenvironment." (PMID 34321580, 2021). "Interleukin-27 (IL-27), which also belongs to the IL-12 family, has been described as a potential anti-tumour therapeutic agent." (PMID 34361105, 2021). "In mouse models of colon carcinoma, IL-27 induced NK cell-mediated cytotoxicity and anti-tumor immunity by activating STAT3 and triggering the expression of perforins." (PMID 33418929, 2021). "The anti-tumor activity of IL-27 inhibits angiogenesis and shifts the phenotype of tumor cells to anti-angiogenic, which disrupts the formation of microvascular networks and inhibits tumor growth and invasion." (PMID 34868907, 2021). "Gene transfer of IL-27 enhanced T cell infiltration into the tumor as well as T cell effector functions and led to a significant reduction in FoxP3+ Treg in tumors to 6.63% compared to 39.8% of FoxP3+ Tregs with control vector." (PMID 32674264, 2020). "Significant reduction of IL-27 in blood was observed when the tumor volume decreased or disappeared." (PMID 32292786, 2020). "In orthotopic tumor bearing mice, intratumoral myeloid cells including granulocytes, TAMs, and dendritic cells (DC) upregulate IL-27 during tumorigenesis." (PMID 33584701, 2020). "Overall the data suggest that if endogenous tumor-specific T cells are engaged sufficiently in PDA, IL-27 in combination with chronic TCR signaling promotes tumor growth by inducing T cell exhaustion." (PMID 33584701, 2020). "In the present work, we sought to examine potential mechanisms for targeted IL-27 enhanced activity directly on tumor cells." (PMID 32046108, 2020). "In this work we sought to examine potential mechanisms for the enhanced activity of targeted IL-27 (IL-27pepL) directly on tumor cells following gene delivery and as compared to controls, utilizing RNAseq." (PMID 32046108, 2020). "We then measured BM levels of IL-27, with demonstrated anti-tumor activity in MM, in 33 patients, including 10 SMM, 13 MMD, and 10 MMR." (PMID 33488620, 2020). "In this study, we show that IL-27 directly induces CXCR3 expression in conventional T cells including tumor antigen specific CD8+ T cells." (PMID 32292786, 2020). "Our group aimed to enhance the efficacy of IL-27 on tumor cells by modifying the cytokine at the C-terminus with a targeting peptide or ligand-targeted approach." (PMID 32046108, 2020). "As both source and target of IL-27, myeloid cells are undoubtedly involved in its dual anti- and pro-tumor activity, which would be contingent on the specific type of tumor." (PMID 32143355, 2020). "A variety of cancer cell types also express IL-27R and respond to IL-27, which can inhibit neoplastic cell proliferation, migration and invasion, and promote apoptotic cell death, revealing direct anti-tumor effects." (PMID 32143355, 2020). "In the present work, we sought to examine potential mechanisms for targeted IL-27-enhanced activity directly on tumor cells utilizing RNA-sequencing (RNAseq)." (PMID 32046108, 2020). "Cytokines regulating PD-L1 expression, including IFN-g, IL-1a, IL-10, IL-27 and IL-32 g, signal through diverse transcription factors and have variable effects on tumor cells and Monos." (PMID 31730010, 2019).
tumor (continued). "Below, we focus on the role of IL-27 and how its anti-tumor potential can be harnessed, as well as how neutralizing the apparent pro-tumor cytokines, IL-30 and IL-35, can further enhance an anti-tumor response in the TME." (PMID 31681561, 2019). "Alternatively, enhancing the probability of IL-27p28 binding with EBI3 to yield IL-27 would increase the abundance of IL-27 in the TME, while decreasing the availability of IL-30, further promoting IL-27 mediated anti-tumor immunity." (PMID 31681561, 2019). "To investigate the selective effects of IL-1a and IL-27 on certain tumor cell lines, we quantified mRNA expression for the subunits of the IL-1a (IL1R1, IL1RAP) and IL-27 receptors (IL27RA, IL6ST)." (PMID 31730010, 2019). "Our results demonstrate that coculture with H-1299 tumor cells leads to the upregulation of IL-6, IL-10, and IL-27 production by CD1c+ DCs compared with that by CD1c+ DCs that were not cocultured with H-1299 cells." (PMID 31921114, 2019). "Understanding the mechanisms of these three cytokines and their complex roles within the TME and the immune landscape is critical for developing therapeutics that promote anti-tumor responses by influencing dynamics between IL-27, IL-30, and IL-35." (PMID 31681561, 2019). "IL-27 is endogenously produced as two separate subunits; however, IL-27p28 (IL-30) can signal alone resulting in tumor progression." (PMID 31681561, 2019). "As an independent cytokine, IL-30 can inhibit gp130 signaling in murine cells giving it the potential to negate the anti-tumor effects that IL-27 provides." (PMID 31681561, 2019). "Taken together, these studies present IL-27 as an anti-tumor cytokine capable of promoting tumor antigen specific CTL development, enhancing their survival, and differentiation into memory effector T cells." (PMID 31681561, 2019). "There is a need to better understand how cytokines like IL-27, IL-30, and IL-35 interact with one another, and how a developing tumor can exploit these interactions to enhance immune suppression." (PMID 31681561, 2019). "Both IL-1a and IL-27 independently and significantly enhanced or induced PD-L1 protein expression on some cultured tumor cell lines, and further increased IFN-g-induced PD-L1 expression in some cases." (PMID 31730010, 2019). "In cancer, IL-27 restricts tumor growth by acting on tumor cells directly, while its role in the tumor microenvironment is still controversially discussed." (PMID 31637217, 2019). "As prominent factors in several essential cellular processes, IL-6 family members are considered pro-tumorigenic, with the exception of IL-27, which has a more complex role in potential anti-tumor therapeutic implications." (PMID 31681561, 2019). "Using the same 14 tumor cell lines that were assessed for the effects of IL-1a and IL-27 on PD-L1 expression as shown in Fig3a and b, respectively, we tested the effects of these cytokines on transcription factor activation." (PMID 31730010, 2019). "Cytokines closely related to IL-12 are being investigated for their anti-tumor capacity, and of these cytokines IL-27 has become an attractive alternative based on its potent anti-tumor activity." (PMID 31681561, 2019). "The impact of IL-27 in tumors was so far attributed to direct suppression of tumor cells, or an altered immune cell infiltrate." (PMID 31637217, 2019). "Adding to this complexity, the newly identified IL-30 cytokine, which shares a subunit with IL-27, promotes tumor progression." (PMID 31681561, 2019). "The direct anti-tumor effects of IL-27 results from its ability to suppress cancer cell proliferation, migration, and invasion, and enhance cancer cell death." (PMID 31681561, 2019). "IL-27 increased PD-L1 expression on Monos as well as dendritic cells, T cells, and some tumor cell lines." (PMID 31730010, 2019). "While our data confirm a tumor-promoting role of IL-27 in the tumor stroma, we uncovered an unexpectedly strong impact of IL-27 signaling on the tumor vasculature." (PMID 31637217, 2019).